GSDMB (gasdermin B)
Diseases named in the same sentence as GSDMB in open-access papers (continued):
Sharing a sentence is not in itself a finding about the gene and the disease.
breast carcinoma (continued). "In breast cancer, the high expression of GSDMB, which is one of the pyroptosis effectors, was related to distance metastasis and poor prognosis." (PMID 37305457, 2023). "Our GEMMs not only validate in vivo the role of GSDMB in human HER2-positive breast cancer but can also be useful for the future development of other tissue-specific and context-dependent disease models." (PMID 35281099, 2022). "Some scholars have pointed out that GSDMB overexpression/amplification occurs in 60% of HER2-positive breast cancers." (PMID 36158689, 2022). "In particular, GSDMB is frequently (> 60%) over-expressed in HER2 breast cancer, mostly due to GSDMB-HER2 co-amplification." (PMID 36163066, 2022). "In contrast, gasdermin B (GSDMB) is upregulated in breast carcinoma and is correlated with increased tumor cell invasiveness and poor survival in patients." (PMID 36189269, 2022). "Previous studies showed that overexpression of GSDMB promoted aggressiveness of breast cancer with poor prognosis, and inhibiting GSDMB expression enhanced the cancer sensitivity to trastuzumab and limited cancer cell invasion in vitro." (PMID 35922531, 2022). "Consistent with the pro-tumor effect of GSDMB in HER2+ human breast carcinomas, R26-GB2/MMTV-NEU GSDMB2-positive mice have double breast cancer incidence than wildtype animals." (PMID 35281099, 2022). "What’s more, in HER2− breast cancer patients, GSDMB expression correlates with elevated metastasis and bad outcomes of patients." (PMID 36119049, 2022). "For example, the expression level of GSDMB in breast cancer cells is higher than that in normal breast tissue and is related to the high metastasis rate and low patient survival rate." (PMID 35311148, 2022). "More research is required to reinstate GSDMB/C/E expression in breast carcinoma cells and create particular GSDMB/C/E agonists or inhibitors to make full use of it for the treatment." (PMID 36119049, 2022). "In particular, the GSDMB shortest translated variant (isoform 2; GSDMB2) increases aggressive behavior in breast cancer cells." (PMID 35281099, 2022). "Overall, our breast cancer models can help to get novel mechanistic insights of the context-dependent role of GSDMB in cancer, and the R26-GB2/MMTV-NEU mice can be potentially used in the future to test novel oncologic treatments in HER2-positive tumors." (PMID 35281099, 2022). "In contrast, GSDMB overexpression is observed in many types of cancers, such as human gastric cancer, hepatocellular carcinoma, colon cancers, cervical cancer, breast cancer, and their corresponding cancer-derived cell lines." (PMID 34858408, 2021). "A few articles regarding the role of GSDMB in oncogeny of few different cancers have been published recently, involving breast cancer, gastric cancer, and cervical squamous cell carcinomas." (PMID 34957313, 2021). "Upregulation of GSDMB was related to poor outcome and increased metastasis in breast cancer patients." (PMID 33634141, 2021). "A previous report showed that the expression level of GSDMB was higher in breast cancer tissues than normal breast tissues." (PMID 33634141, 2021). "The efficacy of GSDMB-targeting therapies was studied in mice bearing HER2 breast cancer xenografts." (PMID 33634141, 2021). "Higher levels of GSDMB have also been correlated with higher rates of metastasis and lower survival rates in breast cancer patients." (PMID 34429144, 2021). "Reports on HER2‐positive breast cancer indicated that overexpression of GSDMB reduced cell viability and promoted the rate of metastasis." (PMID 34369076, 2021). "GSDMB overexpression showed the potential to predict poor clinical outcome in patients with human epidermal growth factor receptor 2 (HER2)-positive breast cancer." (PMID 33634141, 2021). "GSDMB was highly expressed in cancer cells such as breast cancer, stomach cancer, liver cancer, cervical cancer, and colon cancer." (PMID 34778452, 2021).
breast carcinoma (continued). "This discovery suggested GSDMB as a novel for the evaluation and prognosis of breast cancer while another study, the known out of GSDME strongly inhibited PTX‐induced pyroptosis in MCF‐7 breast cancer cell." (PMID 34369076, 2021). "GSDMB markedly increased cell survival to trastuzumab treatment in HER2-positive breast cancer cells." (PMID 33634141, 2021). "Moreno‐Bueno and co‐workers provided evidence that intracellular delivery of an antibody targeting GSDMB reduces aggressiveness of HER2‐positive breast cancer." (PMID 33033617, 2020). "Complementarily, to confirm further the association of GSDMB expression with poor prognosis we evaluated an additional series of 58 HER2-positive (by FISH and IHC) breast cancers." (PMID 27462779, 2016). "GSDMB increases cell growth and reduces apoptosis after trastuzumab treatment in breast cancer cells." (PMID 27462779, 2016). "Consistently, our data in different breast cancer cell lines models as well as in tumor Patient Derived Xenografts (PDXs) indicate that GSDMB promotes cell survival to trastuzumab anti-HER2 immunotherapy." (PMID 27462779, 2016). "We demonstrate that GSDMB is upregulated in breast carcinomas compared to normal breast tissue, being the isoform 2 (GSDMB-2) the most differentially expressed." (PMID 24675552, 2014). "To understand the implication of GSDMB overexpression in breast cancer pathogenesis we first analyzed the phenotypic effect of GSDMB over-expression on the MCF7 breast cancer cell line." (PMID 24675552, 2014). "Our data indicate for the first time that GSDMB, and specifically the isoform 2, is a new marker of breast cancer progression and a potential therapeutic target in order to block tumor growth and cell dissemination." (PMID 24675552, 2014). "Our in vitro analysis in MCF7 cells over-expressing GSDMB-1 and -2 isoforms reveal common and distinct functions of these GSDMB variants in breast cancer progression." (PMID 24675552, 2014). "To explore further the clinical relevance of GSDMB expression in breast cancer, we realized an in silico study combining six breast cancer profiling datasets performed on the HG-U133A Affymetrix microarray platform." (PMID 24675552, 2014). "Our data shows that high levels of GSDMB expression is correlated with reduced survival and increased metastasis in breast cancer patients included in an expression dataset (>1,000 cases)." (PMID 24675552, 2014). "The molecular mechanisms promoting GSDMB over-expression in breast carcinomas, though, remains to be elucidated." (PMID 24675552, 2014). "The analysis of GSDMB expression in a dataset of more than 1,000 human breast cancer tumors reveals that high levels of expression are correlated with reduced survival and increased metastasis." (PMID 24675552, 2014). "Most importantly, we have uncovered that GSDMB promotes a pro-invasive and pro-metastatic role in breast cancer." (PMID 24675552, 2014). "In order to validate the biological involvement of GSDMB-1 and -2 in breast cancer progression, we evaluated their in vivo effect on tumor growth and metastasis using xenograft mouse models." (PMID 24675552, 2014). "Taken together, our results provide for the first time evidences that GSDMB-2 induces invasion, tumor progression and metastasis in MCF7 cells and that GSDMB can be considered as a new potential prognostic marker in breast cancer." (PMID 24675552, 2014). "Next, we evaluated GSDMB expression and its splicing variants in breast cancer tumors as well as normal mammary tissue by qRT-PCR GSDMB gene expression was significantly increased in breast carcinomas compared to normal samples (p = 0.006)." (PMID 24675552, 2014). "In order to evaluate the functional role of GSDMB in breast cancer two GSDMB isoforms were studied (GSDMB-1 and GSDMB-2)." (PMID 24675552, 2014). "To confirm that GSDMB promotes migratory and invasive capacities in breast cancer cells, we analyzed the behavior of HCC1954 after stable knockdown of GSDMB." (PMID 24675552, 2014).
breast carcinoma (continued). "Interestingly, research had shown that there are four isoforms of GSDMB and different isoforms play different roles in breast cancer." (PMID 36823153, 2023). "To test this hypothesis, we focus on breast tumors, since we have previously demonstrated that in mammary carcinomas, GSDMB over-expression has prognostic value and promotes multiple pro-tumor effects in vitro and in vivo." (PMID 36899106, 2023). "Conversely, an antibody-blocking GSDMB can reduce HER2+ breast cancer aggressiveness." (PMID 37627547, 2023). "While further research is required to fully decipher the importance of the autophagy-related functions of GSDMs in disease conditions, our data in patient cohorts with HER2 gastric or breast carcinomas support that GSDMB/Rab7/LC3B-autophagy axis has an impact on clinical behavior." (PMID 36163066, 2022). "Indeed, treated gastric and breast cancer patients with higher puncta tumor expression of both GSDMB/Rab7 and GSDMB/LC3B are more prone to relapse." (PMID 36163066, 2022). "Several studies have shown that the pyroptosis core genes behave differently in different tumors, with GSDMC, GSDMD, and GSDMB acting as oncogenes in colorectal cancer, small-cell lung cancer, and breast cancer, respectively, while GSDME acts as a tumor suppressor in a variety of cancers." (PMID 35769504, 2022). "In breast cancer, cell survival is strongly correlated with GSDMB expression." (PMID 35419279, 2022). "GSDMB is upregulated in some cancers, like breast cancer, gastric cancer, and colon cancer cells." (PMID 35321945, 2022). "For example, GSDMB may act as an oncogene to promote tumorigenesis in the liver, gastric tissues, uterine, cervical and breast cancers." (PMID 34590363, 2021). "Moreover, GSDMB upregulation was associated with reduced therapeutic responses and tumor metastasis in patients with HER2-positive breast cancer." (PMID 33634141, 2021). "Overexpression of GSDMB was capable of enhancing the motility and invasion of breast cancer cells." (PMID 33634141, 2021). "Additionally, in vitro evidence also showed that the anti-GSDMB nanotherapy was able to sensitize GSDMB-expressing breast cancer cells to trastuzumab treatment." (PMID 33634141, 2021). "Oppositely, depletion of GSDMB inhibited the migration and invasion of breast cancer cells." (PMID 33634141, 2021). "Likewise, GSDMB was correlated with trastuzumab resistance phenotype in breast cancer patients derived xenografts." (PMID 33634141, 2021). "GSDMB is significantly more upregulated in breast carcinoma compared to in normal breast tissue." (PMID 34858408, 2021). "To summarize, GSDMB might act as a new biomarker in HER2-positive breast cancer, opening up new opportunities for efficient anticancer therapies." (PMID 33634141, 2021). "Given the high expression and potential tumorigenesis effects of GSDMB, targeting GSDMB might be a therapeutic strategy for gastric, uterine cervix and breast cancers." (PMID 33033617, 2020). "Additionally, we have previously shown that GSDMB over-expression in a breast cancer cell line increased tumorigenic and invasive behaviour." (PMID 27462779, 2016). "Gasdermin-B (the GSDMB gene product) has been shown to promote tumor formation, invasion, and metastasis in mouse xenograft models and the expression of gasdermin-related genes was correlated with reduced survival in breast cancer patients." (PMID 26543765, 2015). "Among GSDMB isoforms, GSDMB-2 seems to be the most expressed isoform in breast cancer tumors." (PMID 24675552, 2014). "Even though there are some previous reports focused on the expression of GSDMB, the function and the hypothetical relevance of GSDMB protein in breast cancer is still unknown." (PMID 24675552, 2014). "We propose that GSDMB could be considered as a new marker of invasiveness and metastasis in breast cancer, although additional studies will be required to fully understand the molecular mechanisms involved." (PMID 24675552, 2014).
breast carcinoma (continued). "Additionally, we examined GSDMB expression in a panel of breast cancer cell lines (MDA-231, MCF7, CAMA-1,T47D, HCC1954) as well as non-tumorogenic cell line (MCF10-2A)." (PMID 24675552, 2014). "The analysis of the expression of this molecule in human breast cancer suggests that GSDMB is over-expressed in breast carcinomas and it could be considered as a potential marker in these tumors." (PMID 24675552, 2014). "Based on these data, we investigated the potential role of GSDMB in breast cancer." (PMID 24675552, 2014). "Here, we uncover for the first time the functional implication of GSDMB in breast cancer." (PMID 24675552, 2014). "Moreover, silencing the endogenous GSDMB in HCC1954 breast carcinoma cells reduces their migratory and invasive capacity." (PMID 24675552, 2014). "Research demonstrates that intracellular administration of GSDMB-specific antibodies can significantly and selectively hinder the metastasis, migration, and therapeutic resistance associated with human epidermal growth factor receptor 2 (HER2)-positive breast cancer." (PMID 38304430, 2024). "Therefore, targeting GSDMB might serve as a promising strategy against HER2-positive breast cancer in the future." (PMID 36823153, 2023). "Interestingly, we demonstrated that GSDMB is a novel therapeutic cancer target, since its multiple pro-cancer functions in HER2+/GSDMB + breast cancer cells were reduced in vitro and in vivo by the intracellular delivery of a GSDMB antibody through biocompatible nanocapsules." (PMID 35281099, 2022). "The inactivation of GSDMB could impair the aggressiveness of HER2-positive breast cancer." (PMID 35541900, 2022). "Those all manifest that GSDMB may be a novel evaluation and prognosticate marker for breast cancer." (PMID 36119049, 2022). "Interestingly, GSDMB could be considered as an oncogene because of its enhanced expression in gastric cancers, hepatic carcinomas, cervical tumors, and breast cancer." (PMID 34298833, 2021). "Therefore, reducing the expression of GSDMB may be a potential therapeutic option for HER2-positive breast cancer." (PMID 33634141, 2021). "Additionally, unlike the reduced expression of GSDMA, GSDMC and GSDMD in gastric and oesophageal cancers, GSDMB is overexpressed in gastric, uterine cervix and breast cancers, indicating that GSDMB may function as a potential oncogene." (PMID 33033617, 2020). "We recently demonstrated that GSDMB over-expression promotes cell motility, invasion and metastasis of breast cancer cell lines, and, intriguingly, it was found over-expressed in breast tumour samples; however, the potential link with breast cancer subtypes remained unexplored." (PMID 27462779, 2016). "The analysis in the TCGA dataset, comprising 534 breast cancers evidenced that patients with tumors expressing high levels of GSDMB showed a significant reduction in overall survival (p = 0.018), while we could not find any association with prognosis for the other members of the family." (PMID 24675552, 2014). "Our results showed that GSDMB-1 and -2 may play a differential role in breast cancer." (PMID 24675552, 2014). "As GSDMB is highly expressed in most HER2 breast cancers and leads to resistance to anti-HER2 treatments, researchers have developed a nanocapsule loaded with an anti-GSDMB antibody and targeted GSDMB-overexpressing cancer cells." (PMID 38066523, 2023). "A study has found that GSDMB is a significant predictor of poor prognosis and therapeutic response in HER2‐positive breast cancer." (PMID 37752941, 2023). "The study in 2019 revealed that delivering the specific anti-GSDMB antibody in biocompatible nanocapsules significantly inhibited the metastasis and drug resistance of HER2 breast cancer cells." (PMID 36482419, 2022). "Gasdermin B (GSDMB) over-expression promotes poor prognosis and aggressive behavior in HER2 breast cancer by increasing resistance to therapy." (PMID 36163066, 2022).
breast carcinoma (continued). "Gasdermin-B (GSDMB) is frequently upregulated in human cancers, especially in HER2-amplified breast carcinomas, and can promote diverse pro-tumor functions (invasion, metastasis, therapy-resistance)." (PMID 35281099, 2022). "Therefore, GSDMB might serve as a potential therapeutic target for the treatment of breast cancer." (PMID 33634141, 2021). "GSDMB, which has been proven as an independent poor prognostic biomarker in breast cancer, is overexpressed in about 60% of HER2 breast cancers." (PMID 34421915, 2021). "Most importantly, further analyses show that GSDMB gene and protein expression predicts poor clinical outcome in HER2-positive breast cancer treated, both in the neoadjuvant and adjuvant settings." (PMID 27462779, 2016). "Together, these results indicate that GSDMB expression/amplification, influences both tumour progression and the response to therapy in HER2-positive breast cancer within the neoadjuvant setting." (PMID 27462779, 2016). "Together, our data reveals GSDMB as a key prognostic and predictive biomarker in HER2-positive breast cancer, highlighting new opportunities for valuable combined therapies." (PMID 27462779, 2016). "In summary, our data identifies the ERBB2 co-amplified and co-expressed gene GSDMB as a critical determinant of poor prognosis and therapeutic response in HER2-positive breast cancer." (PMID 27462779, 2016). "Our analysis of GSDMB over-expression in the breast cancer cell tumor model MCF7 demonstrates that it promotes cell motility, invasion and metastasis whereas GSDMB silencing strongly reduced migration and invasion in HCC1954 breast cell line." (PMID 24675552, 2014). "Furthermore, upregulation of gasdermine B (GSDMB), a member of the Gasdermin (GSDM) genes, in HER2 breast cancer promotes poor prognosis, aggressive, and resistant to anti-HER2 agents through elevating protective autophagy." (PMID 39075259, 2024). "Moreover, over-expressed GSDMB contributes to resistance to chemotherapy and anti-HER2 therapies in HER2-positive breast cancer patients." (PMID 36823153, 2023). "Additionally, many studies have also proposed that GSDMB possessed protumor functions such as migration, metastasis, and resistance to therapy in HER2 breast cancer." (PMID 34298833, 2021). "Knockout GSDMB, or intracellular-delivered anti-GSDMB through nanocapsules could neutralize the effects of GSDMB, reduce the aggressiveness of HER2 breast cancer, and enhance the sensitivity to trastuzumab." (PMID 34421915, 2021). "Moreover, both isoforms of GSDMB, GSDMB1 and GSDMB2, promote invasion and metastasis of the MCF7 breast carcinoma cell line in vitro, whereas silencing of these isoforms in the HCC1954 breast carcinoma cell line significantly decreased migration and invasion." (PMID 34858408, 2021). "Additionally, GSDMB gene amplification and protein overexpression predict the poor clinical outcomes to HER2‐targeted therapy in HER2‐positive breast cancer." (PMID 34590363, 2021). "Furthermore, Molina‐Crespo et al159 developed nano‐sized anti‐GSDMB antibodies to suppress the migration and metastasis of HER2 breast cancer in vitro and in vivo." (PMID 34590363, 2021). "GSDMB expression and not the expression of other GSDMs, was significantly elevated in HER-2 positive breast cancer and associated with poor survival." (PMID 34830775, 2021). "In conclusion, our study has identified GSDMB as a relevant biomarker of poor prognosis that is also able to predict non-response to current standard therapy for HER2-positive breast cancer." (PMID 27462779, 2016). "Overall these results and our previous data firmly establishes GSDMB as a negative prognostic marker in HER2-positive breast cancer patients treated (trastuzumab plus chemotherapy) in both the neoadjuvant and adjuvant settings." (PMID 27462779, 2016).